CXCL2 (C-X-C motif chemokine ligand 2)
Diseases named in the same sentence as CXCL2 in open-access papers (continued):
Sharing a sentence is not in itself a finding about the gene and the disease.
tumor (575 papers, 2007 to 2026). "Various CXC chemokine receptors are upregulated in HCC tumor cells, with CXCL2 and CXCL8 released by tumor-associated monocytes and with CXCL12 released by cancer-associated fibroblasts (CAFs) and stromal cells." (PMID 40721870, 2025). "For instance, sphingolipid metabolites can influence the expression of chemokines such as CXCL2, thereby promoting the infiltration of tumor-associated macrophages, which in turn enhances tumor growth and metastatic potential." (PMID 40823076, 2025). "In advanced-stage OSCC, higher P.g., neutrophil extracellular traps, CXCL2, and tumor-associated neutrophils correlated with poor prognosis." (PMID 40924302, 2025). "While P. gingivalis was able to promote oral cancer progression in C57BL/6 mice, which was associated with its ability to recruit tumor-associated neutrophils (TANs) through the activation of the CXCL2/CXCR2 signaling in the tumor microenvironment." (PMID 40361452, 2025). "For instance, biglycan activates Toll-like receptors (TLR4 and TLR2) on macrophages, promoting TNF-α and MIP-2/CXCL2 expression, which sustains tumor-associated inflammation." (PMID 41281748, 2025). "The expression and significance of CXCL2 in tumors have garnered significant attention, potentially serving as a diagnostic marker for various tumors, a detection factor for tumor recurrence, and a promising therapeutic target." (PMID 41378129, 2025). "P.g. and F.n. also stimulate tumor-associated neutrophils via CXCL2/CXCR2, accelerating tumor invasion." (PMID 40924302, 2025). "Strong expression of P.g., CXCL2, and tumor-associated neutrophils was observed in advanced stages (III–IV) of OSCC, while weaker expression was found in early stages (I–II)." (PMID 40924302, 2025). "Under low PLK1 condition, TME is characterized by a higher proportion of tumor infiltrating lymphocytes and a lower level of CXCL2, and this condition is associated with more M1 polarization and functional antigen presentation pathway." (PMID 38885192, 2024). "Egfl6 induces phosphorylation of Syk to promote activation of IL-10 and Cxcl2 in tumor-associated myeloid cells to drive immunosuppression." (PMID 39312740, 2024). "Tumor-associated fibroblasts can release a variety of chemokines and cytokines, such as IL-6 and CXCL2, to promote the migration and aggregation of Tregs cells into the TME, thereby transforming TME into an immunosuppressor." (PMID 39600941, 2024). "Signaling through CXCL1 and CXCL2 is mainly responsible for recruitment of immune suppressive tumor associated neutrophils as well as PMN-MDSC." (PMID 37964379, 2023). "Our results firstly indicated distinct LRs profiles between mutation-like and wildtype-like cells, where mutation-like tumor cells were specifically more likely to secret chemokines such as CXCL2/CXCL3 to communicate with other cells." (PMID 38097680, 2023). "Firstly, CXCL2 (one ligand of CXCR1/2) was associated with tumor-associated neutrophil recruitment in the KIRC and CM datasets." (PMID 37540227, 2023). "CXCL1 and CXCL2 are also associated with tumor progression, including tumor growth, angiogenesis, and metastasis via enhancing cell proliferation and the invasion of cancer cells." (PMID 36661524, 2023). "Taken together, abrogating MCP expression results in a near-complete blockade of tumor monocyte recruitment and a compensatory influx of neutrophils, which is associated with increased expression of Cxcl, Cxcl2 and Gm-csf." (PMID 37012245, 2023). "Previous studies demonstrated that CXCL2 chemokine is the major secreted factor from Ptenpc−/−; Trp53pc−/− tumor linked to M2 polarization of macrophages both in vitro and in the TME." (PMID 37055829, 2023). "In the mouse tumor tissues, Trim11 deficiency also upregulates the expression of Cxcl1, Cxcl2 and Cxcl3." (PMID 36192394, 2022).
tumor (continued). "CXCL2 can recruit myeloid-derived suppressor cells and tumor-associated macrophages and increase immunosuppressive effects, thus enhancing cancer cell proliferation, invasion, and metastasis." (PMID 35912252, 2022). "CD73 expression in tumor cells was most strongly associated with inflammatory signaling pathways, including chemokine secretion (CXCL2), major histocompatibility complex class I (MHC-I) expression, and interferon signaling." (PMID 35973991, 2022). "CXCL5 and CXCL2 levels were high in tumor cells and tumor-associated stroma in a mouse model of PDA." (PMID 33603130, 2022). "CXCL2 expression was positively associated with the abundance of several tumor-infiltrating immune cells, including neutrophils, immature dendritic cell (iDC), macrophages, type 1 T helper cell (Th1), and natural killer (NK) cells." (PMID 36276119, 2022). "Meanwhile, inflammatory factors, such as CCL2 and CXCL2, facilitate the recruitment and infiltration of tumor-associated immune/inflammatory cells, such as TAMs and MDSCs, into the TME." (PMID 34768524, 2021). "These cells also express high levels of Cxcr2 and Cxcl2 genes, which are associated with tumor progression and metastasis." (PMID 32719347, 2020). "Conversely, in esophageal squamous cell carcinoma IL-17 stimulated CXCL2 production by tumor cells, which is also associated with increased infiltration of neutrophils." (PMID 33262763, 2020). "In prostate cancer the chemokines CXCL1 and CXCL2 have been implicated in promoting tumour associated bone disease by upregulating osteoclastogenesis, and in turn promoting tumour cell survival." (PMID 27761371, 2016). "This hapten-tumor IgM will also lead to the activation of mast cells which will release TNFα and CXCL2, causing cause FasL+, perforin+ neutrophil cell infiltration." (PMID 24949488, 2014). "In early-stage MF, we observed gene expression differences in cells of both the stroma and the immune system, with keratinocytes exhibiting increased interferon response and proliferation (STAT1, ICAM1, HLA-DRA, GJB2), while fibroblasts displayed tumour-associated programs (CXCL2, TNFAIP6, CEBPD)." (PMID 41888970, 2026). "Additionally, the presence of P. gingivalis in OSCC tissues was associated with the expression of CXC motif chemokine ligand 2 (CXCL2) and tumor-associated neutrophils (TANs)." (PMID 40361452, 2025). "Relative to the other AD samples, both AD5 and the AYA group exhibited higher expression of genes associated with aggressive tumor features and inflammation (e.g., CXCL2, TUBB3, RRM2, and MMP1) and lower expression of differentiation markers and metastatic regulators (e.g., KIT and NCAM1)." (PMID 41374320, 2025). "Moreover, high expression of CXCL2 in tumor tissue in the RNAseq dataset was associated with significantly reduced FFLF." (PMID 38653773, 2024). "Similarly, CXCL2 is known to drive neutrophil recruitment, a phenotype associated with “cold” tumor immune microenvironments." (PMID 37968341, 2024). "Moreover, high expression of CXCL2 in tumor tissue (RNAseq dataset) was associated with a reduced FFLF (p = 0.0031)." (PMID 38653773, 2024). "Moreover, when comparing canine OSCC tumor gene expression to normal oral mucosa, two differently expressed genes associated with the presence of TAMs and MDSCs were identified: CXCL2, CD70." (PMID 36698398, 2022). "Similarly, PMNs in the NC410 plus bintrafusp alfa group had significantly lower expression of Cxcl2, which encodes a chemokine known to attract PMNs and myeloid-derived suppressor cells and to modulate tumor cell plasticity, compared with all other groups." (PMID 35230974, 2022). "Several lines of evidence highlighted the critical role of CXCL2 in recruiting tumor-associated neutrophils and promoting their secretion of pro-inflammatory, angiogenic and immunoregulatory factors, therefore, contributing to tumor progression and metastasis." (PMID 36605208, 2022).
tumor (continued). "In addition, several of our invasion-specific signature genes are chemokines including CXCL1, CXCL2, and IL-8 which have been implicated in the promotion of tumor-associated angiogenesis, a critical feature of invasive tumors." (PMID 17611626, 2007). "Furthermore, the upregulation of CXCL8 (IL-8) and CXCL2 observed in our 3D spheroid cultures may contribute to the recruitment and accumulation of tumor-associated neutrophils within TME." (PMID 39193365, 2024). "VEGF signaling may induce CXCL2 secretion by tumor-associated macrophages (TAMs) or other cell types, attracting more monocytes into the tumor microenvironment through immune cell recruitment at the tumor site." (PMID 39770551, 2024). "Overall, the increased upregulation of CXCL9 and CXCL10, accompanied with the downregulation in CXCL2, may underlie the observed alterations in the cellular components at the level of systemic organs and within the tumor microenvironment following combination treatment." (PMID 36605208, 2022). "Meaningfully, CXCL2 overexpression combined with anti‐PD‐1 therapy exhibited prominent tumor inhibition in mouse models." (PMID 41114470, 2026). "The results demonstrated that the combined overexpression of CXCL2 with PD‐1 blockade markedly attenuated tumor growth and weight." (PMID 41114470, 2026). "In contrast, CXCL2 overexpression retained its tumor‐suppressive effects in mice depleted of CD8+ T cells or macrophages." (PMID 41114470, 2026). "The results revealed remarkable increases in the expression levels of the neutrophil chemokines CXCL1 and CXCL2 within the tumor tissues after the intratumoral injection of LPS." (PMID 39799561, 2025). "Meanwhile, CXCR2- CXCL2, along with CCR5-CCL5 obviously up-regulated in tumor-adjacent tissue, and they are linked with better OS, except for CXCL10." (PMID 40087771, 2025). "For instance, Zhen Bao’s research on the role of SNAIL in EMT demonstrated its promotion of CXCL2 secretion by mesenchymal cells, which enhances the infiltration of M2 macrophages and drives tumor metastasis." (PMID 40777130, 2025). "Subsequently, the elevated CXCL2 secretion from tumor cells promotes the recruitment of myeloid‐derived suppressor cells (MDSCs) into the tumor microenvironment (TME) through C‐X‐C chemokine receptor type 2 (CXCR2), thereby facilitating CRC progression." (PMID 40213993, 2025). "The enhanced release of HMGB1 from pyroptotic tumor cells subsequently increases the expression of CXCL2 in neighboring tumor cells, which recruit MDSCs into the tumor microenvironment, thereby promoting CRC development." (PMID 40213993, 2025). "Using bioinformatics techniques, we conducted in-depth analysis and validation of the relationship between SERPINA3 and CXCL2 in the tumor microenvironment, elucidating their role in macrophages." (PMID 40367014, 2025). "IL‐1β also promotes MDSC differentiation by triggering the secretion of chemokines like CXCL1 and CXCL2, which attract MDSCs to the tumor site, thus reinforcing the tumor‐promoting functions within the TME." (PMID 39558859, 2025). "CXCR2 is not only activated by CXCL1 but also by several other CXC chemokines, including CXCL2, CXCL3, CXCL5, CXCL6, and CXCL8, all of which are closely associated with cancer progression and the tumor microenvironment." (PMID 40490643, 2025). "Compared with control, Vox led to a slight decrease (not significant) of Cxcl1 expression in cancer cells, to a strong downregulation of Cxcl5 in total immune cells and macrophages, and to a modest upregulation of Cxcl2 in tumor macrophages." (PMID 40139833, 2025). "In PDAC, P. gingivalis, an important pathogenic bacterium in the oral cavity, can promote the secretion of chemokines (CXCL1 and CXCL2) in the tumor microenvironment (TME), thereby recruiting tumor-associated neutrophils (TANs) in the TME to release NETs." (PMID 40102723, 2025).
tumor (continued). "Owing to the high expression of CXCL2/5 in the HSCs of tumor-bearing mice, we examined the expression levels of chemokines in tumor-activated LX2 (aLX2) cells." (PMID 41214328, 2025). "In prostate cancer lacking PTEN, activated JAK2/STAT3 signaling established an immunosuppressive tumor microenvironment via SASP factors such as CXCL1, CXCL2, and IL-6 and resulted in tumor growth and chemoresistance." (PMID 40862837, 2025). "Neutrophils are recruited to the brain prior to tumor cell arrival via tumor-derived factors, such as G-CSF, CXCL2 and TGF-β." (PMID 41219968, 2025). "CXCL2 also plays a critical role in immune infiltration and modulation of the TME via its interaction with tumor-associated macrophages (TAMs) and neutrophils." (PMID 40589738, 2025). "Neutralizing CXCL2 in the culture supernatant of DTX2‐overexpressing tumor cells and neutrophils partially restored IFNγ expression and proliferation of CD8+ T cells, while neutralizing CXCL6 did not." (PMID 39733452, 2025). "CXCL1 and CXCL2 sustain chronic inflammation and facilitate tumor development by interacting with the CXCR2 receptor." (PMID 40430079, 2025). "High expression of the ligands of Cxcr2, such as Cxcl1, Cxcl2, Cxcl3, and Cxcl5, was observed mainly in tumor cells, fibroblasts, chondrocytes, pericytes and osteoclasts among APM‐naïve cells." (PMID 40433925, 2025). "This dual function is well documented in melanoma, which expresses chemokines such as CCL2, CCL5, CXCL1, CXCL2, CXCL3, and CXCL8 which have been implicated in tumor growth and progression." (PMID 40943634, 2025). "Temozolomide (TMZ), a common alkylating agent used in adjuvant chemotherapy for HGG, has been shown to upregulate the CXCL8-dependent CXCL2/CXCR2 axis, promoting angiogenesis and the recruitment of tumor-associated macrophages." (PMID 41432874, 2025). "The results confirmed that the mRNA expression levels of Cxcl1 and Cxcl2 were decreased in Il7r-KO tumor cells, while the expression of Cxcl3 remained unchanged." (PMID 41360767, 2025). "To identify which cells in the liver recruit M-LDNs and increase lipid accumulation, we compared the expression levels of CXCL2 in various cells in the livers of tumor-bearing and tumor-free mice." (PMID 41214328, 2025). "Next, we confirmed the expression of these CXCLs by immunofluorescence staining and found that CXCL2 was highly expressed in E‐cad+ tumor cells." (PMID 40213993, 2025). "TANs are neutrophils recruited to tumor sites via chemokines (including CXCL1, CXCL2, and IL-8) secreted by tumor cells and stromal cells." (PMID 40771826, 2025). "To further elucidate the involvement of pivotal regulators CXCL2 in Fn-enhanced tumor growth and macrophage M2 polarization, we used a selective inhibitor SB225002 for CXCR2 (the receptor for chemokines CXCL2)." (PMID 38637499, 2024). "Prior research has demonstrated a mediating role of CXCL2 in bidirectional crosstalk between tumor cells and TAMs." (PMID 38637499, 2024). "Using multiple KRAS-driven human LUAD cell lines, our work demonstrates that STK11 loss results in altered tumor-intrinsic cytokine expression, including but not limited to IL-6, CXCL8 and CXCL2." (PMID 37968341, 2024). "This possibly suggests that, while CXCL5 production is more isolated to tumor cells, CXCL2 appears mostly produced by stromal components, such as infiltrating immune cells." (PMID 38339310, 2024). "CLL cells and tumor-associated stromal cells also produce and secrete FGF-2, TNF-α, CXCL-12, CXCL-2, NGAL, IGF-1, progranulin, and angiogenin." (PMID 39796700, 2024). "Treatment of tumor stromal organoids in culture with docetaxel induces cytokine secretion (Csf3, Csf2, Il-6, Cxcl1, Cxcl2, and Tnfα) into the cell culture media while reducing levels of Vegf." (PMID 39338937, 2024). "In line with the mRNA expression, IHC showed that Cxcl2 was abundantly expressed in non-tumor cells of a-PD-L1- and IgG-treated Egfl6-2F8c tumors compared to their control 2F8c tumors." (PMID 39312740, 2024).
tumor (continued). "The study revealed that CA-MSCs highly express CXCR1/2 ligands such as CXCL1, CXCL2, and IL-8, which promote monocyte differentiation towards a pro-tumor M2 phenotype, facilitating tumor progression and the acquisition of chemotherapy resistance." (PMID 38779660, 2024). "Under high PLK1 condition, TME is characterized by low tumor infiltrating lymphocytes and high secreted CXCL2, which promotes M2 polarization and disrupts antigen processing and presentation." (PMID 38885192, 2024). "This suggests that both IL-10 and Cxcl2 mediate, at least in part, Egfl6-dependent tumor immunosuppression." (PMID 39312740, 2024). "Four signaling pathways—TGFβ (related to SRC), IL-1 (related to FOS), CXCL, and VEGF (related to CXCL2), were highlighted due to their significant roles in tumor occurrence, progression, and deterioration." (PMID 39770551, 2024). "The bacterium promotes the activation of neutrophil chemotaxis in the tumor microenvironment (TME) by increasing the secretion of the chemokine CXCL2, which contributes to tumor transformation and progression." (PMID 39339011, 2024). "AKT/NF-κB pathway is involved in tumorigenesis and tumor development and is reported to be a downstream signaling pathway of CXCL2." (PMID 39759028, 2024). "It is known that, upon binding to the CXCR2 receptor, CXCL2 recruits MDSCs to the tumor sites in a paracrine and autocrine manner, promoting tumor progression." (PMID 39312740, 2024). "qPCR and western blotting identified tumor cells as a significant source of CXCL2 post-cryoablation, suggesting that cryoablation induces tumor cells to secrete CXCL2, which interacts with CXCR2 on neutrophils, increasing their infiltration." (PMID 39648199, 2024). "Similar to the gene expression analysis of BM CD11b+ cells isolated from Egfl6 mice, CD11b+ cells isolated from 2F8c-Egfl6 tumors displayed higher IL10, Cxcl2, Clec5a, and Ceacam1 gene expression compared with tumor controls." (PMID 39312740, 2024). "Our findings also demonstrated that MH treatment reduces CXCL2 expression, which plays a crucial role in recruiting intratumoral granulocytic MDSCs and promoting their pro-tumor immunosuppressive function." (PMID 38444857, 2024). "Stimulated ESCC tumor cells to release more CXC chemokines CXCL2 and CXCL3 and enhanced the killing ability of neutrophils." (PMID 39906741, 2024). "Our results indicate that, compared with tumor controls, TAMs infiltrating Egfl6+ tumors exhibited upregulation of Cxcl2, whereas PMN-MDSCs isolated from Egfl6+ tumors showed upregulation of both IL-10 and Cxcl2." (PMID 39312740, 2024). "In a more detailed analysis, we found that among 28 subsets of tumor-infiltrating lymphocytes, 22 were correlated with CXCL2, 21 with CXCL12, 15 with CXCL14, and 19 with CXCL17." (PMID 38232115, 2024). "SNAIL not only recruits M2 macrophages to infiltrate the tumor center by promoting the secretion of CXCL2 but also indirectly regulates the expression of CXCL2 through the NF-κB pathway and directly modulates CXCL2 expression by binding to its promoter region." (PMID 38605400, 2024). "Correlations between the expression of CXCL2/12/14/17 and the abundance of tumor-infiltrating lymphocytes." (PMID 38232115, 2024). "Esc and Zeb1/Snail OE tumors expressed lower levels of gMDSC-recruiting cytokines and chemokines than parental and EV tumor cells, including G-CSF, GM-CSF, IL-1a, and CXCL2." (PMID 38378697, 2024). "The combination treatment, Egfl6 NAb and a-PD-L1, was associated with (a) a reduced number of intratumoral PMN-MDSCs and TAMs, (b) reduced PMN-MDSC and TAM secretion of IL-10 and Cxcl2, and (c) increased tumor infiltration of antitumor MHC-II+ macrophages." (PMID 39312740, 2024). "CXCL2 is viewed as a cancer-supporting chemokine providing tumor cells with proliferative, survival, and angiogenic cues." (PMID 38338661, 2024).